HLA-G (major histocompatibility complex, class I, G)
Diseases named in the same sentence as HLA-G in open-access papers (continued):
Sharing a sentence is not in itself a finding about the gene and the disease.
colorectal cancer (continued). "In the current study, HLA-G expression in 457 primary colorectal cancer lesions was analyzed with immunohistochemistry, and the differential lesion HLA-G expression for prognostic stratification with traditional prognosticators was analyzed." (PMID 29296176, 2017). "Nonetheless, these novel findings presented here for the role of HLA-G 3’UTR region in prognosis of colorectal cancer provide the basis for implementation of personalized cancer treatments." (PMID 26633805, 2015). "Dichotomising HLA-G expression based on positive expression (> 0% positive cells) or a 5%-cut-off has previously been used in prognostic biomarker studies on patients with colorectal cancer." (PMID 35027037, 2022). "Furthermore, both HLA-G and HLA-E expression are correlated with poor survival and tumor metastasis in colorectal cancer." (PMID 32560316, 2020). "Similarly, miR-133 reduced HLA-G protein expression in trophoblast cell lines, and its low expression in primary colorectal cancer samples, in which the HLA-G levels are high, suggested a possible inverse correlation of these molecules." (PMID 32733439, 2020). "Percentage of HLA-G expression in serial section of colorectal cancer lesions." (PMID 33329527, 2020). "Percentage of HLA-G expression in different zones of colorectal cancer lesions." (PMID 33329527, 2020). "Moreover, expression levels of HLA-G or HLA-E and the combined expression of both molecules were all negatively correlated with OS of colorectal cancer patients." (PMID 27652273, 2016). "HLA-G aberrant expressions have been observed in a variety of human cancers including cutaneous melanoma, mesothelioma, glioma, hematopoietic and trophoblastic tumors; lymphoproliferative disorders and carcinoma of lung, ovary, endometrium, bladder, breast, kidney, gastric and colorectal carcinoma." (PMID 39703498, 2024). "They revealed that the co-expression of ILT4 and HLA-G in tissues of human primary CRC and their mutual interaction promotes the progression of human colorectal cancer." (PMID 35626255, 2022). "In this study, the expression of HLA-G (n=157), ILT-2/4 (n=82), and PD-L1 (n=70) in epithelial cell adhesion molecule (EpCAM)-positive colorectal cancer (CRC) cells was analyzed by multicolor flow cytometry, and the prognostic significance of these molecules was evaluated." (PMID 34054869, 2021). "Summary, our preliminary findings revealed that novel unidentified HLA-G isoforms recognized by mAbs 5A6G7 but not 4H84 might be existed in colorectal cancers." (PMID 30234020, 2018).
asthma (32 papers, 2006 to 2025). "Further studies analyzed the potential interaction among maternal asthma, microRNA regulation of soluble HLA-G in the airway and offspring subsequent risk for asthma." (PMID 35082780, 2021). "UTR2-H10 was associated with asthmatic exacerbation within the previous 12 months and eosinophil count, and UTR7 (HLA-G*01:01:03:03-H16) was associated with acute asthma recurrence." (PMID 29527207, 2018). "Individual variation in HLA-G expression is linked to its genetic polymorphism and has been associated with many pathological situations such as asthma, which is characterized by epithelium abnormalities and inflammatory cell activation." (PMID 29527207, 2018). "The 3 ́ UTR of the asthma susceptibility gene HLA-G is targeted by three different miRNAs: miR-148a, miR-148b, and miR-152." (PMID 28362264, 2017). "The +3142 C/G SNP, which is located in the 3′UTR of the HLA-G gene, affects the targeting of miR-148a, miR-148b, and miR-152 and interacts with mother's asthma status to determine risk of asthma in the child." (PMID 27413762, 2016). "HLA-G genetic polymorphisms confer susceptibility to airway hyperresponsiveness and asthma development." (PMID 27413762, 2016). "In fact, HLA-G genetic polymorphisms confer susceptibility to airway hyperresponsiveness and asthma development." (PMID 27413762, 2016). "The binding of miRNAs to HLA-G is modulated by a SNP in the HLA-G 3′UTR that is associated with asthma risk (rs1063320)." (PMID 27652273, 2016). "For example, a SNP in the 3′-UTR of asthma susceptibility gene HLA-G influences the targeting of miR-148a, miR-148b, and miR-152." (PMID 24991086, 2014). "HLA-G was recently identified as an asthma susceptibility gene, and expression of a soluble isoform, HLA-G5, has been demonstrated in human airway epithelium." (PMID 23327606, 2013). "Recent studies in asthmatic families and in a birth cohort at high risk for developing asthma suggest a role for HLA-G in asthma susceptibility." (PMID 23327606, 2013). "Tan and colleagues described that a single nucleotide polymorphism in the 3'UTR of HLA-G, a known asthma-susceptibility gene, disrupts the binding sites of three miRNAs (miR-148a, miR-148b, miR-152) targeting this gene." (PMID 21092244, 2010). "Although evidence showed that childhood and adult asthma differed in several parameters, the associations between PHF11, DPP10, HLA-G and asthma or asthma-related phenotypes were found in both groups." (PMID 19951440, 2009). "For PHF11 and HLA-G, the associations with asthma or asthma-related phenotypes were only significant at the nominal level, and became not significant after the adjustment for multiple testing." (PMID 19951440, 2009). "Associations between SNPs in PHF11, DPP10, HLA-G and asthma or asthma-related phenotypes, adjusted for age, gender, height, weight, BMI and smoking status." (PMID 19951440, 2009). "Associations between haplotypes in PFH11, DPP10, HLA-G and asthma-related phenotypes, adjusted for age, gender, height, weight, BMI and smoking status." (PMID 19951440, 2009). "This region contains the HLA locus and the HLA-G gene within this region has previously been identified as a potential asthma and BHR susceptibility gene using four cohorts (including the Dutch cohort used in the current analyses)." (PMID 18442398, 2008). "They suggested that miR-148b may contribute to the risk of asthma by regulating the HLA-G-a molecule with immunomodulatory properties." (PMID 38085380, 2023). "The development of asthma is characterized by abnormalities in the bronchial epithelium and the activation of inflammatory cells, which, as research has shown, is also associated with the HLA-G genetic polymorphism." (PMID 34948145, 2021). "Although the HLA-G gene was identified as an asthma susceptibility gene and SNPs -964 and 3142 were associated with asthma, no study so far has described the haplotypes effect, shown to be more relevant than SNPs to predict sHLA-G dosage, in asthma clinical studies." (PMID 29527207, 2018).
asthma (continued). "HLA-G protein expression and genetic polymorphisms have been reported to be associated with asthma." (PMID 28303134, 2017). "HLA-G is a known susceptibility gene for asthma and therefore it has previously been proposed that miR-148b-3p might overtake a role in asthma susceptibility by interacting with HLA-G." (PMID 29231896, 2017). "Finally, they observed that individuals with G allele of rs1063320 had reduced asthma-related exacerbations, thus suggesting that rs1063320 modifies the effect of statin benefit in asthma by modulating HLA-G expression through mir-148b and -152." (PMID 27652273, 2016). "Three miRNAs; miR-148a, miR-148b, and miR-152 have been reported to affect HLA-G expression, suggesting that miRNA mediated mechanisms may contribute to the impact of HLA-G on asthma risk." (PMID 27658857, 2016). "We found that DPP10 was significantly associated with bronchial hyperresponsiveness (BHR) and BHR asthma after the adjustment for multiple testing; while the associations of PHF11 with positive skin reactions to antigens and the associations of HLA-G with BHR asthma were only nominally significant." (PMID 19951440, 2009). "The mechanisms responsible for tissue-specific expression and interindividual HLA-G expression variation are of utmost importance since HLA-G expression is associated with many diseases involving immune system surveillance and inflammatory disease, such as asthma." (PMID 29527207, 2018). "Thus, it is likely that the association of the HLA-G gene to asthma-susceptibility may be due to the allele-specific regulation of this gene by miRNAs." (PMID 21092244, 2010). "Upregulation of HLA-G expression can also be observed in macrophages in asthma with severe chronic inflammation, in mast cells in the liver and lung, and in kidney fibrosis." (PMID 41181133, 2025). "Although the role of HLA-G in asthma is unclear, this protein interacts with T, B, and natural killer cell receptors to modulate immune responses by blocking and/or inhibiting their functions in both soluble and membrane-bound isoforms." (PMID 37373658, 2023). "A role for HLA-G in asthma pathogenesis is further suggested by the demonstration of sHLA-G molecule expression in the airway epithelium and of increased levels of sHLA-G in plasma and bronchoalveolar lavage (BAL) fluid of children with atopic asthma." (PMID 35082780, 2021). "The potential role of HLA-G in asthma has been also reported in a Brazilian study evaluating the HLA-G untranslated region (3′UTR) in 115 asthmatic patients stratified according to disease severity (mild, moderate, and severe) and in 116 healthy individuals." (PMID 35082780, 2021). "In this context, HLA-G 5’-UTR methylation was associated with HLA-G gene silencing and HLA-G 3’-UTR with a common SNP rs1063320 was reported to modulate binding of miRNA-148/152 family and suppress soluble HLA-G expression in asthma." (PMID 30410504, 2018). "In pathological settings, fewer functional HLA-G molecules and differential expression of HLA-G isoforms were observed in asthma and prostatic adenocarcinoma patients, respectively." (PMID 30319626, 2018). "Because airway inflammation in asthma involves a Th-2 skewing of lymphocytes similar to pregnancy, HLA-G is an attractive candidate molecule for promoting the immune profile characteristic of asthma." (PMID 27413762, 2016). "In this article, we examined the associations of polymorphisms in the identified top regions of PHF11, DPP10, and HLA-G with asthma and asthma-related phenotypes in a Chinese population, using a population-based study design." (PMID 19951440, 2009). "HLA-G In single-SNP analyses, compared with the rs1736935 C/C homozygotes, individuals with T/T genotype had a lower risk of BHR asthma (OR = 0.64, nominal P = 0.044)." (PMID 19951440, 2009). "We previously showed that HBEC express HLA‐G according to genetics and asthma status." (PMID 35988034, 2022).
asthma (continued). "As indicated in the literature, the HLA-G molecule also affects the type of asthma occurring." (PMID 34948145, 2021). "In vitro studies have indicated that the presence of HLA-G may differ from the physiological status in asthma." (PMID 34948145, 2021). "The research indicates that the HLA-G molecule may be an important biomarker of asthma development and potentially more broadly influencing the immune system, especially in the context of modulating local immunity in the mucosa." (PMID 34948145, 2021). "A dysregulation of HLA-G isoforms in an asthma context could lead to both an impaired immunoregulatory capacity and altered epithelium differentiation properties." (PMID 28303134, 2017). "In asthma, HLA-G expression was found to be increased in lung tissues." (PMID 28303134, 2017). "A role for HLA-G in asthma pathogenesis was further suggested by the demonstration of the expression of the sHLA-G5 isoform in the airway epithelium and of increased circulating plasma levels of sHLA-G in children with atopic asthma." (PMID 27413762, 2016). "Further, HLA-G production may in turn be regulated by the pleiotropic, immunoregulatory cytokine IL-10 which may in the context of asthma further regulate T cell profiles and function." (PMID 23327606, 2013). "HLA-G then may be an attractive candidate molecule for modulating specific T cell profiles that are important in asthma." (PMID 23327606, 2013). "Associations in genetic variations in the promoter region and in a microRNA target site in the 3’UTR of HLA-G suggested that dysregulated expression may contribute to asthma pathogenesis." (PMID 23327606, 2013). "Allele-specific targeting of HLA-G, a non-classical HLA class I locus, by miR-148a and miR-148b, is associated with risk of asthma." (PMID 23139801, 2012). "It is probably due to the small effect sizes of the genetic variants and lack of power in the current study that the associations of PHF11 and HLA-G with asthma or asthma-related phenotypes failed to reach the study-wide significance level." (PMID 19951440, 2009). "While the role of HLA-G in airway inflammation and asthma remains to be defined, its presence, particularly in greater abundance in asthmatic airways and in plasma of asthmatic subjects, suggests that epithelial cell expression may be of importance in airway inflammation." (PMID 23327606, 2013). "Thus decreased production of IL-10 in asthma might in turn lead to changes in HLA-G expression." (PMID 23327606, 2013). "Among genes identified in asthma GWAS, ROBO1, RORA, HLA-DQB1, IL2RB and PDE10A showed most consistent expression patterns and from asthma candidate genes, e.g. NOD1, EDN1, CCL5 and HLA-G were identified." (PMID 21699702, 2011). "Six asthma candidate genes, ADAM33, NPSR1, PHF11, DPP10, HLA-G, and CYFIP2, located at different chromosome regions have been positionally cloned following the reported linkage studies." (PMID 19951440, 2009). "However, differential expression of some asthma genes was consistent in both developing human and murine lung, e.g. NOD1, EDN1, CCL5, RORA and HLA-G." (PMID 21699702, 2011). "While there was no general over-representation of asthma genes among differentially expressed genes, some asthma genes were consistently differentially expressed in multiple developing lung transcriptomes, e.g. NOD1, EDN1, CCL5, RORA and HLA-G suggesting key functional roles in lung development." (PMID 21699702, 2011). "HLA-G transcriptional isoforms were quantified by real-time PCR in human bronchial epithelium cells (HBEC) grown in air–liquid interface culture obtained from five healthy controls (HC), seven patients with mild asthma (MA), and seven patients with severe asthma (SA)." (PMID 28303134, 2017).
asthma (continued). "Airway inflammation associated with Th2 cytokines such as IL-4 and IL-13 is a principal feature of asthma, but whether these cytokines elicit expression of HLA-G is not known." (PMID 23327606, 2013). "We have recently demonstrated increased presence of soluble HLA-G in bronchoalveolar lavage fluid recovered from subjects with mild asthma versus control, non-asthmatic subjects; this may represent on-going attempts to suppress (incompletely or unsuccessfully) airway inflammation." (PMID 23327606, 2013). "Although there is no direct evidence yet for this hypothesis in asthma, in other contexts HLA-G has been shown to suppress dendritic cells and T cells that participate in inflammation, and to activate CD4+CD25+FoxP3+ regulatory T cells that can suppress cells that participate in airway inflammation." (PMID 23327606, 2013). "Thus, both bronchial epithelium structural remodeling and impairment in inflammation resolution observed in asthma could be the result of HBEC intrinsic defects, embodied here by HLA-G isoform expression, rather than immune cell dysfunction." (PMID 28303134, 2017).
cervical carcinoma (32 papers, 2008 to 2025). A carcinoma arising from either the exocervical squamous epithelium or the endocervical glandular epithelium. "An increasing number of studies have shown that HLA-G expression is associated with disease progression in patients with cervical cancer." (PMID 36053326, 2023). "To summarize, we developed and validated a novel prognostic risk model for cervical cancer based on HLA-G-driven DEGs, and the prognostic signature showed great ability in predicting the overall survival of patients with cervical cancer." (PMID 35924232, 2022). "The aim of this study was to evaluate the potential role of soluble HLA-G (sHLA-G), its genetic polymorphisms and its haplotype structure in the susceptibility and prognosis of primary cervical cancer in a Chinese Han population." (PMID 36618382, 2022). "They concluded that HLA-G polymorphism is a strong and independent risk factor for cervical cancer development." (PMID 36010256, 2022). "This study aimed to develop and validate a prognostic risk model by screening the immune checkpoint molecule HLA-G and its DEGs in cervical cancer based on RNA sequencing (RNA-seq) and the TCGA dataset by a series of bioinformatics methods." (PMID 35924232, 2022). "In our study, we established and validated, for the first time, a novel prognostic risk model for cervical cancer based on HLA-G-driven DEGs by using a series of bioinformatics methods." (PMID 35924232, 2022). "Increasing evidence suggests that HLA-G expression is strongly associated with high-grade tumour and poor prognosis in patients with cancer, especially lung cancer, colorectal cancer, cervical cancer." (PMID 35924232, 2022). "Consistent with previous studies, HLA-G expression was associated with the developmental stage of cervical cancer and non-small-cell lung cancer (NSCLC) patients." (PMID 34276642, 2021). "In the future, there will be a need for additional studies to obtain deeper insight into the association between HLA-G expression levels and advanced cervical cancer." (PMID 32670296, 2020). "Our previous findings indicated that HLA-G expression was associated with disease progression in cervical cancer." (PMID 30619504, 2018). "To test the effect of the HLA-G polymorphism on the progression of cervical lesions from CIN1 to cervical cancer in the HPV18 group, we carried out a separate analysis restricted to normal histology, CIN1 and CIN2+." (PMID 30619504, 2018). "In cervical cancer, we and others have described loss of classical HLA class I, and expression of HLA-E and HLA-G at the site of the primary tumor." (PMID 27895918, 2016). "Previous studies, including cervical cancer, also reported on HLA-G upregulation in case of classical HLA loss." (PMID 27895918, 2016). "The alleles HLA-G 14bp INS, +1537C (rs12722477), G*01:01, G*01:04, and G*01:06 have been associated with both high-grade squamous intraepithelial lesions and cervical cancer, while HLA-G 14bp DEL and +3142C alleles have been identified as protective." (PMID 25477881, 2014). "After multivariate Cox regression analysis, eight genes were identified as key predictors of HLA-G-driven DEGs in the prognostic risk model for predicting the overall survival of patients with cervical cancer, including CD46, LGALS9, PGM1, SPRY4, CACNB3, PLIN2, MSMO1, and DAGLB." (PMID 35924232, 2022). "Moreover, our previous findings also indicated that HLA-G expression was associated with disease progression in cervical cancer." (PMID 30619504, 2018). "Similarly, a recent publication exploring the association between HLA-G expression and cervical cancer progression also focused on high-grade lesions only." (PMID 23265140, 2012). "However, the distribution of HLA-G alleles, genotypes, and haplotypes in cervical cancer patients and their possible roles in the expression of HLA-G levels remain unclear." (PMID 36618382, 2022).